BRAF (B-Raf proto-oncogene, serine/threonine kinase)
Diseases named in the same sentence as BRAF in open-access papers (continued):
Sharing a sentence is not in itself a finding about the gene and the disease.
melanoma (continued). "One immediate consequence of this observation is the suggestion that co-treatment with inhibitors of BRAF and PC could be a promising anti-melanoma therapy." (PMID 35148308, 2022). "Studies have shown that the BRAF inhibitor vemurafenib can reduce related immunosuppressive signals, facilitate infiltration of lymphocytes, and reduce immunosuppressive cells, as well as enhance the presentation of melanoma antigens." (PMID 36077696, 2022). "A similar pseudo-dormant and reversible drug-tolerant phenotype have also been reported in other oncogenic contexts, such as glioblastoma, BRAF-mutant melanoma, colorectal cancers, breast cancers, or pancreatic cancer, treated either with targeted therapies or chemotherapies." (PMID 35681591, 2022). "We have shown that ctDNA is a feasible source of genetic material for BRAF mutation assessment in clinical practice in advanced melanoma patients, especially when a tissue sample is not available or in patients with rapidly progressive disease." (PMID 35159044, 2022). "To begin assessing the possibility that imipramine could have a similar immunostimulatory effect in other tumor types, we treated the iBIP2 GEMM of BRAF-driven melanoma." (PMID 36113478, 2022). "The author could not find a report that describes this co-occurrence in clinical samples however a recent mouse study demonstrated that KMT2D functions as tumor suppressor in BRAF V600E mutant melanomas." (PMID 36275468, 2022). "Genetically, melanoma has been classified based on driver mutations activating the MAPK signaling pathway as (I) BRAF-mutant (50–60%), (II) RAS-mutant (20–30%), (III) NF1-mutant (10–15%) or (IV) triple (BRAF, NRAS and NF1) wild-type melanoma (~10%)." (PMID 36077603, 2022). "Eosinophils significantly induce apoptosis in melanoma cells, which could be reinforced by additional treatment with BRAF-/MEK-inhibitors." (PMID 35565423, 2022). "In contrast, melanomas from chronically sun-damaged skin or from sites not routinely exposed such as acral or mucosal sites do not typically carry BRAF mutations and would be more associated with NRAS and KIT mutations respectively." (PMID 35712493, 2022). "Moreover, augmented BRAF copy numbers have also been detected in around 20% of cases of B-Raf inhibitor therapy resistance in melanoma." (PMID 36143375, 2022). "It has been reported, that NTRK fusions and typical oncogenic drivers, such as BRAF, NRAS, GNAQ and GNA11 are mutually exclusive and NTRK fusions might be more common in BRAF or NRAS wild-type melanomas." (PMID 35993275, 2022). "Upregulation of EGFR and platelet-derived growth factor receptor (PDGFRβ) by TGF-β signaling leads to resistance to BRAF and MEK inhibitors, and upregulation of PDGFRα by the Sonic Hedgehog Homolog (Shh) pathway confers resistance to BRAF inhibition in metastatic BRAF(V600E) melanoma." (PMID 36483040, 2022). "The molecular mechanisms regulated by SEMA6A to sustain tumor aggressiveness and targeted therapy resistance were investigated in vitro by using BRAF-mut and BRAF-wt melanoma cell lines, an inducible SEMA6A silencing cell model and a microenvironment-mimicking fibroblasts-coculturing model." (PMID 35440004, 2022). "We chose 6 mg/kg of DMF and 25 mg/kg of Vem in our study, which correspond to the human dose given orally to psoriatic patients at 240 mg twice daily and the human dose given orally to patients with BRAF-mutant melanoma at 960 mg twice daily (as measured per kilogram body weight), respectively." (PMID 35141161, 2022). "Immunotherapy and BRAF inhibitors are breakthrough for the treatment of CM, but many patients develop resistance due to extensive and molecular intra- and inter-tumoral heterogeneity of melanoma cells." (PMID 35820816, 2022).
melanoma (continued). "In this way, the understanding of BRAF status with the additional epigenetic studies, such as miRNAs, could predict the evolution of melanoma tumors at the time of diagnosis or during treatment." (PMID 35326682, 2022). "YUGEN8, a BRAF-mutated (V600E) and PTEN-null, short-term culture, established from a patient with BrM was subjected to in vivo and in vitro selection, and yielded several clonally related melanoma cell line variants with low or high brain-metastatic potential." (PMID 35737114, 2022). "Interestingly, miR-211 has also been detected in melanoma sEVs and was shown to be induced upon treatment with the BRAF inhibitors vemurafenib and dabrafenib." (PMID 35804857, 2022). "The BRAF V600E mutation in melanoma activates the MAPK pathway to trigger melanocyte cell aberrant proliferation, inhibits the aberrant melanocyte cell apoptosis and eventually promotes melanoma progression." (PMID 36551302, 2022). "However, SOD also appears to play a role in BRAF-inhibitor resistance in melanoma cell lines as BRAF inhibition of drug-naive melanoma cell lines induces elevated free radical formation." (PMID 35326683, 2022). "The frequent presence of both BRAF mutations and FGF2 overexpression in melanomas, which lack a recognized systematic therapy so far, leads to the combination of FGFR inhibitor PD166866 and BRAF V600E inhibitor, consequently increased cell apoptosis and restricted tumor growth." (PMID 35494629, 2022). "BRAF V600 mutant ctDNA could be useful as a biomarker and early predictor of acquired resistance in patients with BRAF V600 mutant melanoma." (PMID 36058945, 2022). "However, the relatively immediate development of resistance to these drugs is a clinical problem, in part because BRAF inhibitor-resistant (BRAFi-R) melanoma cells exhibit more progressive behavior, in particular enhanced migration, invasion and metastasis." (PMID 36551563, 2022). "A longer median PFS (16.2 vs. 12.0 months, respectively; p = 0.042) with a higher rate of grade 3 adverse events (55% vs. 33%) were also reported in dabrafenib, and trametinib plus spartalizumab than dabrafenib and trametinib for BRAF(V600)-mutant advance melanoma." (PMID 36145516, 2022). "Besides the activating mutations in the BRAF and NRAS oncogenes, found in significant proportions of primary melanomas, important epigenetic changes occur in melanoma." (PMID 36443814, 2022). "In addition, the Melanoma Inhibitory Activity (MIA) protein has been found to be expressed in BRAF V600E mutant melanocytes, suggesting a potential role for MIA in melanocyte OIS." (PMID 36551868, 2022). "There is also a rationale for the role of MYC in melanoma resistance to BRAF/MEK inhibitors." (PMID 35565444, 2022). "However, it has to be noted that increased miR-125b expression has been found in melanoma cells resistant to BRAF inhibitors and in tumor samples from BRAF-inhibitor-treated patients." (PMID 35326682, 2022). "Although inhibitors of the MAPK pathway remain a common therapeutic strategy in malignant melanoma, many trials have focused on patients harboring BRAF-V600E mutations, without similar enrollment opportunities for patients with BRAF fusion-positive tumors." (PMID 35326655, 2022). "ZIC5 knockdown also induced cell death in BRAF inhibitor‐resistant melanoma cells." (PMID 36282887, 2022). "The IDTC phenotype of melanoma cells is not susceptible to certain treatments, such as a combination of BRAF inhibitors with oligomycin, HDACIs, and AKT inhibitors." (PMID 36224606, 2022). "Besides reactivating MAPK, PI3K/Akt and EGFR signaling have also been involved in BRAF inhibitor resistance in melanoma." (PMID 36210843, 2022). "In melanoma patients treated with BRAF inhibitors a characteristic side effect can be observed with high frequency, development of benign epithelial tumors (keratoacantoma, papilloma) or malignant ones (squamous cancer) as well as new nevi or induced novel melanomas." (PMID 36213163, 2022).
melanoma (continued). "Overall, our results indicate that SEMA6A contributes to microenvironment-coordinated evasion of melanoma cells from dual BRAF/MEK inhibition and it might be a good candidate predictor of short-term benefit from dual BRAF/MEK inhibition." (PMID 35440004, 2022). "Although BRAF/MEK inhibitors constitute one of the main backbones of treatment in melanoma, little is known about their impact on GM and how this might correlate with immune re-induction." (PMID 36233289, 2022). "In addition, amplifications at EGFR, BRAF V600E, NRAS and KRAS loci, mutations of NRAS, KRAS and MAP2K1, and PTEN loss are often observed in resistant lesions of melanoma and CRC patients with treatment of combined RAF targeted therapies 85-87." (PMID 35966590, 2022). "lj‐2‐66 inhibited the proliferation of BRAF‐mutant melanoma cells in a dose‐dependent manner." (PMID 35332658, 2022). "We were next interested in testing the hypothesis that UHMK1 depletion would improve response and delay resistance following treatment with the current standard of care for BRAFV600 melanoma patients, a BRAF + MEK inhibitor combination." (PMID 35232962, 2022). "In addition, a direct effect of nintedanib on CAF in vivo is also possible regarding the described paradoxical activation of CAF upon BRAF inhibition in melanoma." (PMID 35156321, 2022). "CAFs induce resistance not only in immunotherapy but also to BRAF inhibitors in advanced melanoma." (PMID 35409404, 2022). "Recurrent BRAF and NRAS mutations are well documented in melanoma." (PMID 35326655, 2022). "In melanoma, resistance to BRAF inhibitors has become one such complication." (PMID 36551563, 2022). "Finally, we subjected SOX10+ (MM383) and SOX10– (IGR-39) melanoma cell lines to increasing concentrations of BRAF inhibitor." (PMID 36040798, 2022). "The results showed that patients with advanced melanoma without BRAF mutations had significantly improved overall survival (OS) after receiving nivolumab treatment." (PMID 36230724, 2022). "Combination herpes simplex virus (HSV) oncolytic virotherapy and BRAF inhibitors (BRAFi) represent promising immunogenic treatments for BRAF mutant melanoma, but an improved understanding of the immunobiology of combinations is needed to improve on the benefit of immune checkpoint inhibitors (ICI)." (PMID 35338089, 2022). "Additionally, two phase 3 trials (COMBI-d and COMBI-v) demonstrated improved effects of the combination of BRAF (dabrafenib) and MEK (trametinib) inhibitors compared to monotherapy BRAF inhibition for advanced melanoma." (PMID 36358601, 2022). "Here we confirmed that the inhibition of MAPK leads to the modulation of several molecules that affect NK immune response and that BRAF-mutant melanoma cell lines, sensitive to vemurafenib, respond to the combination of BRAF and MEK inhibitors in a very similar manner to single inhibition." (PMID 36726591, 2022). "Indeed, based on the encouraging results achieved in melanoma, several studies have investigated the association between BRAF and MEK inhibitors in BRAF mutant NSCLC." (PMID 35454926, 2022). "This was similarly appreciated in the International Neoadjuvant Melanoma Consortium (INMC) pooled analysis of neoadjuvant BRAF/MEK inhibitor use in patients with clinical stage III melanoma, showing that achieving a pCR, but not a pPR, correlated with improved RFS9,22,23." (PMID 36289334, 2022). "Robust predictions are also provided for the BRAF subgroup of melanoma patients." (PMID 36139469, 2022). "Importantly, SREBP-1 inhibition can sensitize resistant mutant BRAF melanoma both in vitro and in vivo models." (PMID 35406721, 2022). "For patients with resected stage IIIA (metastasis > 1 mm), IIIB and IIIC melanoma (AJCCv7) harbouring the BRAF V600E or V600K mutations, the COMBI-AD trial demonstrated significantly improved RFS with combination BRAF/MEK inhibitors dabrafenib and trametinib compared with placebo." (PMID 35639333, 2022).
melanoma (continued). "The resistance of melanoma to BRAF inhibitors remains a tough clinical challenge." (PMID 36700470, 2022). "In this study we further characterized the 13C-metabolic profile in response to BRAF/MEK targeted therapies in YUMM1.7 syngeneic melanoma xenografts characterized for BrafV600E/wt Pten−/− Cdkn2−/−, allowing the use of immunocompetent mice to fully integrate all aspects of the tumor microenvironment." (PMID 35327519, 2022). "High‐CSD melanomas have a threefold higher TMB than low‐CSD melanomas, but we found that neither high‐CSD nor BRAF mutant melanoma were associated with survival." (PMID 35924450, 2022). "These authors also investigated whether YY1 mediated autophagy could modulate the activity of one of the commonly used in melanoma patients BRAF inhibitors – vemurafenib." (PMID 35719931, 2022). "Combination of cobimetinib with Vem was first approved in 2015 for treating melanomas harboring BRAF mutations and were not eligible for surgical excision or were metastatic." (PMID 35141161, 2022). "In addition, VEGF-A derived from melanoma cells induces resistance to vemurafenib by the induction of VEGF receptor (R)-1 on BRAF inhibitor-sensitive counterparts." (PMID 35409404, 2022). "Though NF1 mutations ordinarily happen in CMs lacking mutations in BRAF or NRAS, nearly 4% of melanomas with mutations in BRAF or NRAS also exhibit NF1 mutations." (PMID 36143375, 2022). "FAK-mediated survival signaling confers melanoma resistance to BRAF inhibitors." (PMID 35163650, 2022). "Interestingly, SMARCB1-depleted melanoma cells were more resistant to BRAF inhibitors but more sensitive to BCL2 inhibitors, providing additional evidence that SMARCB1 expression can influence sensitivity to therapeutics." (PMID 35323214, 2022). "Furthermore, the pharmacological inhibition or knockdown of YAP in BRAF inhibitor resistant melanoma cells decreased ERK1/2 signaling, remodeling of the actin cytoskeleton and tumor growth and therefore enhanced BRAF inhibitor efficacy." (PMID 36119516, 2022). "Others used a mouse model of syngeneic BRAF(V600E)-driven melanoma." (PMID 36358912, 2022). "Most importantly, while MYC overexpression induced resistance to BRAF inhibitors in melanoma cells in vitro, it also sensitized the cells to inhibitors of glucose metabolism, glutaminolysis and other metabolic processes, pointing to actionable MYC‐induced metabolic dependencies." (PMID 36214609, 2022). "The majority of non-CSD types, including trunk melanoma, exhibit BRAF gene V600E mutations (60%) or NRAS mutations (20%)." (PMID 35356202, 2022). "High levels of ZEB1, correlating with Fra-1 expression and melanoma stemness markers (MITFlo/p75hi in CSCs vs MITFhi/p75lo in non-CSCs) are implicated in intrinsic resistance to BRAF and MEK inhibitors." (PMID 35326630, 2022). "Melanomas most often harbor mutations that affect the Ser/Thr kinase BRAF (50%), the small GTPase NRAS (25%), or the negative regulator of RAS, neurofibromin 1 (NF1) (14%), resulting in increased RAS/mitogen-activated protein kinase (MAPK) signaling." (PMID 36309522, 2022). "Activating mutations in these genes may not only promote the development of melanoma but also reduce the effectiveness of BRAF/MEK inhibitors as a result of activation of the MAPK pathway despite the inhibition of BRAF kinase." (PMID 35565444, 2022). "The aim of our analysis is to describe prescription patterns, recurrence, and toxicity rates of adjuvant treatments for resected stage III/IV melanoma in daily practice, including comparing physicians’ preferences for ICI versus BRAFi/MEKi for BRAF V600E/K mutant melanoma." (PMID 35336796, 2022). "Importantly, the inhibition of this ECM signaling cascade, using the MT1-MMP selective inhibitor ND322 restored melanoma cell sensitivity to BRAF inhibitor treatment." (PMID 36119516, 2022).
melanoma (continued). "Combining DCA and CB-839 might also be effective in melanoma cells resistant to BRAF inhibition, which inherently display more oxidative metabolism and glutamine dependence." (PMID 35409102, 2022). "In addition, several studies have involved the phenotype switching of melanoma cells as an escape route to CM-targeted therapies using BRAF inhibitors." (PMID 35053440, 2022). "In addition to BRAF, melanomas have the activity of many signalling pathways related to oncogenesis, including PI3/Akt kinase, NFB, Src and STAT3." (PMID 36613640, 2022). "BRAF is the main oncogene found in both malignant melanoma and in benign nevi." (PMID 35883768, 2022). "Our previous results indicated the inhibitory effect of lj‐2‐66 on BRAF‐mutant melanoma cells." (PMID 35332658, 2022). "In this context, monitoring of BRAF-mutant alleles could act as an identifier of residual disease and an early indicator of progression, as it has been displayed in BRAF-mutant melanoma." (PMID 36230877, 2022). "Interestingly, histone deacetylase (HDAC) proteins function as an apoptosis suppressor in melanoma cells, being part of the BRAF-inhibitor resistance mechanisms." (PMID 36358912, 2022). "Likewise, inhibiting BRAF signaling in therapy-responsive melanoma patients led to downregulated SREBP-1 expression and subsequent hinderance of lipogenesis." (PMID 35884561, 2022). "It has been observed that NF1 inactivating mutations occur in melanomas without BRAF and NRAS mutations and cause the activation of the MAPK pathway." (PMID 36614156, 2022). "BRAF mutations appear in the first stages of melanocytic tumors, whereas individual studies indicated that BRAF mutations have an unfavorable prognosis in patients with melanoma, which has not been definitively shown in other studies." (PMID 36614156, 2022). "Typically, these panels only cover driver mutations in genes known to be involved in melanoma, such as BRAF, NRAS, KRAS, KIT, GNAQ, and GNA11, and do not include genes that have been recently found by WES/WGS studies." (PMID 36431075, 2022). "This activation was also confirmed by histological analysis of our MBM mouse models of human and murine melanoma bearing different BRAF mutations (intracardially inoculated mCherry-labeled WM115 [BRAF V600D], D4M.3A [BRAF V600E], or 131/4-5B1 [BRAF V600D] melanoma cells)." (PMID 35980743, 2022). "Interestingly, BRAF inhibitor treatment has also been implicated in activating MAFs to remodel the ECM making it stiffer, which induced drug tolerance in melanoma cells." (PMID 36119516, 2022). "This phenomenon was described in melanoma tumors treated with cisplatin or BRAF/MEK inhibitors." (PMID 35956175, 2022). "NGFR signaling also plays a critical role in acquired melanoma resistance to BRAF/MEK inhibitors." (PMID 36291794, 2022). "Hence, the combination of these modalities for the treatment of patients with B-Raf proto-oncogene, serine/threonine kinase (BRAF)-mutant melanoma is worthy of investigation." (PMID 35493449, 2022). "Outstanding response predictions for BRAF/MEK inhibitors are preferentially enriched in melanoma cell lines, while other drugs such as EGFR inhibitors exhibit cancer-type agnostic iGenSig scores, consistent with the tumor-type related clinical activities of these drugs." (PMID 35618721, 2022). "Thus, activated fibroblasts and the rigidity of the matrix provide a sanctuary for melanoma cells to survive BRAF targeting." (PMID 36324182, 2022). "BRAF targeted therapy can induce rapid tumor response in BRAF-mutant melanoma and improve survival." (PMID 36290885, 2022). "By contrast, in the BRAF mutated melanoma patient subgroup, PD-L1+ PMN frequencies failed to predict patient ORR to nivolumab whereas were inversely associated with DCR." (PMID 36016960, 2022). "As a BRAF inhibitor, vemurafenib shows great clinical benefit and has been approved by the United States Food and Drug Administration (FDA) as the first-line treatment for BRAF-mutated melanoma." (PMID 36210843, 2022).